IDH1 (isocitrate dehydrogenase (NADP(+)) 1)
Diseases named in the same sentence as IDH1 in open-access papers (continued):
Sharing a sentence is not in itself a finding about the gene and the disease.
coronary artery disease (3 papers, 2021 to 2025). "In Kattih at al.’s paper, the presence of IDH1 mutations was associated with a higher rate of coronary artery disease." (PMID 37297022, 2023). "Mutant IDH1 patients exhibited a significantly higher prevalence of coronary artery disease (26.1% vs. 6.4%, p = 0.002)." (PMID 32948843, 2021).
Crohn disease (3 papers, 2022 to 2023). A gastrointestinal disorder characterized by chronic inflammation involving all layers of the intestinal wall, noncaseating granulomas affecting the intestinal wall and regional lymph nodes, and transmural fibrosis. "In our series, one combined PCC-NOS and SRC carcinoma (with an SRC component accounting for 30% of the neoplastic growth) arising in a 39-year-old woman affected by Crohn disease showed an IDH1 pathogenic mutation." (PMID 36812376, 2023). "The single IDH1-mutated SB-PCC arose in a patient with Crohn disease and was histologically classified as a combined poorly cohesive NOS and SRC carcinoma." (PMID 36812376, 2023). "We compared the frequency of alterations in all recurrent genes in CAC by IBD subtype, and PIK3CA and IDH1 alterations were significantly enriched in patients with a history of Crohn’s disease versus ulcerative colitis." (PMID 36611031, 2023). "In addition, we identified, albeit rarely, potentially targetable alterations, such as IDH1 or ERBB2 mutations or MMRd/MSI, in such aggressive cancers, most of which (80%) were associated with Crohn disease." (PMID 36812376, 2023).
diffuse large B-cell lymphoma (3 papers, 2019 to 2025). "IDH1 expression was upregulated in several hematologic malignancies, including angioimmunoblastoma, mesenchymal large-cell lymphoma, peripheral T-cell lymphoma, and diffuse large B-cell lymphoma (DLBCL)." (PMID 36497259, 2022). "A gene expression profile analysis of the cancer genome atlas (TCGA) dataset identified IDH1 upregulation in several hematological malignancies, including angioimmunoblastic lymphoma, anaplastic large cell lymphoma, peripheral T cell lymphoma, and diffuse large B cell lymphoma (DLBCL)." (PMID 31010244, 2019).
gallbladder cancer (3 papers, 2020 to 2025). "Comparing ICC with gall bladder cancer, ICC has significantly higher IDH1 (14.5%), BAP1 (9.5%), and PBRM1 (7.5%) mutation rates." (PMID 38203635, 2023).
hemangioma (3 papers, 2021 to 2025). A benign vascular lesion characterized by the formation of capillary-sized or cavernous vascular channels. "Recently, somatic mosaic IDH1 R132C variant in DNA derived from hemangioma tissue but absent in DNA derived from the blood was identified in an adult male with MS." (PMID 35765075, 2022). "Initial functional studies suggest that the IDH1 R132C mutation is likely the primary mutation responsible for the development of enchondromas, while the ERC2 L309I mutation is probably a causative mutation underlying the pathogenesis of hemangiomas." (PMID 34790172, 2021).
liver fibrosis (3 papers, 2017 to 2025). "Notably, disrupted minor intron splicing activated glutamine reductive metabolism for de novo lipogenesis through induction of Idh1, which caused accumulation of ammonia in the liver, thereby initiating hepatic fibrosis upon LXR activation." (PMID 40100939, 2025). "Clearance of ammonia or suppression of IDH1 activity reversed hepatic fibrosis and MASH progression." (PMID 40100939, 2025). "Furthermore, CAT, BLVRB, NXN, PRDX1, and IDH1 may be candidates for detection of liver fibrosis or therapeutic targets for the treatment of liver fibrosis." (PMID 28830339, 2017). "Furthermore, CAT, BLVRB, NXN, PRDX1, and IDH1 may be candidates for the detection of liver fibrosis or therapeutic targets for the treatment of liver fibrosis." (PMID 28830339, 2017).
mastitis (3 papers, 2017 to 2021). Inflammation of breast tissue during lactation or postpartum due to an obstructed duct or infection. "The significance of the LOC407171, PTPRC, ABCG2, and IDH1 genes in the turquoise module was confirmed using DT models and attribute weighting, highlighting their critical roles in mastitis." (PMID 34691146, 2021). "In addition, if the last feature exceeded 14.390 and the expression of IDH1 was present, PTPRC would be classified as having mastitis." (PMID 34691146, 2021).
myeloid leukemia (3 papers, 2015 to 2023). A clonal proliferation of myeloid cells and their precursors in the bone marrow, peripheral blood, and spleen. "Our mechanistic findings are in contrast to an earlier report, which suggested that in non-solid tumors (myeloid leukemia) Bcl-2 antagonism is synthetically lethal with mutated IDH1 or IDH216." (PMID 29057925, 2017).
prostate adenocarcinoma (3 papers, 2020 to 2022). "Although IDH1 has a role in various tumors, its clinical relevance and its expression in response to the immune response have not been investigated in prostate adenocarcinoma (PRAD)." (PMID 35132321, 2022).
small cell lung carcinoma (3 papers, 2020 to 2024). Small cell lung cancer (SCLC) is a highly aggressive malignant neoplasm, accounting for 10-15% of lung cancer cases, characterized byrapid growth, and early metastasis. "For example, non-YAP1-driven small cell lung cancer (SCLC) and brain tumors with IDH1/2 mutations represent cancer subsets that are suitable for HDAC-targeted therapy." (PMID 38225241, 2024). "We further reveal that small cell lung cancer (SCLC) and isocitrate dehydrogenase (IDH1/2)-mutant brain tumors show enrichment of pro-ferroptosis gene signature, suggesting a unique vulnerability of SCLC and IDH-mutant tumors to ferroptosis inducers." (PMID 33167414, 2020).
Thrombocytopenia (3 papers, 2018 to 2024). A reduction in the number of circulating thrombocytes. "Multivariate analysis indicated that progression to thrombocytopenia and ASXL1 and IDH1 mutations were associated with poor overall survival." (PMID 39574914, 2024). "The multivariate analysis revealed that progression to thrombocytopenia (p = 0.042, hazard ratio (HR) = 7.7, 95% confidence interval (CI) = 1.04–7.70), ASXL1 mutation (p = 0.041, HR = 9.91, 95% CI = 1.05–9.91), and IDH1 mutation (p = 0.02, HR = 75.6, 95% CI = 5.19–1103) were associated with poor OS." (PMID 39574914, 2024).
undifferentiated pleomorphic sarcoma (3 papers, 2021 to 2023). An undifferentiated soft tissue sarcoma characterized by the presence of a pleomorphic malignant cellular infiltrate. "The presence of IDH1/IDH2 mutations helps distinguish CS from chondroblastic osteosarcoma and DDCS from undifferentiated pleomorphic sarcoma (UPS) of bone." (PMID 36926116, 2023).
acute liver failure (2 papers, 2024). Rapid deterioration of liver function causing encephalopathy and coagulopathy. "IDH1-K93 and MDH1-K118 mutations reduce acetylation of IDH1 and MDH1, which promotes the formation of NETs and aggravates the progression of acute liver failure." (PMID 38172700, 2024). "In a mouse model of ALF, deacetylation of IDH1 and MDH1 resulted in NETosis and promoted the progression of acute liver failure." (PMID 38172700, 2024). "Therefore, we speculate that deacetylation of IDH1 and MDH1 may promote acute liver failure by regulating NETosis." (PMID 38172700, 2024).
bile duct cancer (2 papers, 2021 to 2022). "According to several completed trials, FDA approved agents targeting IDH1 and FGFR2 for bile duct cancers progressing after standard chemotherapy." (PMID 36199981, 2022).
breast neoplasm (2 papers, 2017 to 2023). A benign or malignant neoplasm of the breast parenchyma. "Basal human breast tumours also carried protein expression outliers in IDH1, EGFR and MAP2K1." (PMID 28348404, 2017).
cerebral astrocytoma (2 papers, 2022 to 2024). An astrocytoma that arises from the cerebral hemispheres. "In contrast to cerebral astrocytoma to which they are classically associated, IDH mutations are rare in IMA, especially for canonic mutations (IDH1 p.R132H and IDH2.R172H)." (PMID 39001480, 2024). "In our experimental setup, we had pediatric high-grade cerebellum and cerebrum astrocytoma without mutations in IDH1/2 and H3F3A." (PMID 36293551, 2022).
colitis (2 papers, 2020 to 2025). Inflammation of the colon. "Additionally, IDH1 mutations may be more prevalent in colitis-associated CRC and could indicate unique metabolic and epigenetic changes." (PMID 40102272, 2025). "In colitis-associated CRC, MYC amplifications and IDH1 mutations are more frequent compared to sCRC." (PMID 40102272, 2025). "More recent studies observed IDH1 mutations in 7% of inflammatory bowel disease-associated (IBD) CRC and 11% of colitis-associated CRC, compared to 1% of sporadic CRC, providing a therapeutic target in these types of CRC tumors." (PMID 32610612, 2020).
colon adenocarcinoma (2 papers, 2021 to 2023). "We first cloned IDH1-R132H into the lentiviral plasmid pLV-EF1α-FLAG-IRES-Puro and produced pLV-EF1α-IDH1-R132H-FLAG-IRES-Puro lentiviruses, which were used to infect CT26 colon adenocarcinoma cells." (PMID 37741882, 2023).
diabetic cardiomyopathy (2 papers, 2025). Diabetic cardiomyopathy is a disorder of the heart muscle in people with diabetes. "Therefore, IDH1 may be associated with cuproptosis.The role of IDH1 in diabetic cardiomyopathy has been scarcely studied, and further investigations are still required in the future." (PMID 41144543, 2025). "Notably, GSTK1 and UGT2B subfamily members co-regulate Chemical carcinogenesis-DNA adducts, Drug metabolism-Cytochrome P450, and extracellular exosome signaling, while IDH1/SDHB/SDHD link TCA cycle defects to redox imbalance in diabetic cardiomyopathy and tumorigenesis." (PMID 40626307, 2025).
fatty liver (2 papers, 2014 to 2025). "Inhibition of IDH1 activity substantially blocked induction of de novo lipogenesis in hepatocytes and hepatic steatosis, inflammation, and especially fibrosis in mice with defective minor intron splicing." (PMID 40100939, 2025). "As a result, hepatic steatosis, fibrosis, and ammonia accumulation were largely diminished in the livers of IDH1 activity–inhibited ZLKO mice." (PMID 40100939, 2025).
gliomatosis cerebri (2 papers, 2019 to 2024). A diffuse glial tumor which infiltrates the brain extensively, involving more than two lobes. "One of them was a patient with IDH1 wild-type gliomatosis cerebri that could not be further characterized." (PMID 38326438, 2024).
hepatitis viral ( (2 papers, 2021 to 2022). "Furthermore, liver fluke-negative clusters 3 and 4 can be subdivided based on immune-related pathway enrichment (for cluster 3), and IDH1/2 mutations, FGFR2 fusion, and hypermethylated CpG promoter shores associated with viral hepatitis (for cluster 4)." (PMID 35433771, 2022).
Hydrocephalus (2 papers, 2016 to 2020). Hydrocephalus is an active distension of the ventricular system of the brain resulting from inadequate passage of CSF from its point of production within the cerebral ventricles to its point of absorption into the systemic circulation. "In other various factors except ep-MRI and adverse effects, we found only tendencies for negative staining for isocitrate dehydrogenase 1 (IDH-1) mutation (P = 0.074), and delayed hydrocephalus (P = 0.096)." (PMID 26726015, 2016).
invasive ductal carcinoma (2 papers, 2018 to 2024). "A study looking at tissue expression of IDH1 in patients carrying invasive ductal carcinoma showed that IDH1 levels decreased as the cancer progressed." (PMID 39282472, 2024).
liver disease (2 papers, 2021 to 2024). "Other relatively strong positive associations are found between liver disease etiology and genes IDH1 and ARID1A (phi = 0.82 and phi = 0.77 for HCV and HIV infection, respectively), and a moderate association was also observed between HBV infection and GNAS (phi = 0.68)." (PMID 34885159, 2021).
malaria (2 papers, 2021 to 2025). Malaria is a serious and sometimes fatal disease caused by a parasite that commonly infects a certain type of mosquito which feeds on humans. "Isocitrate Dehydrogenase (NADP(+)) 1 (IDH1) is one of the genes we identified as down-regulated in severe malaria has also been found to be associated with HIV infection." (PMID 34746025, 2021).
metastatic melanoma (2 papers, 2019 to 2022). A melanoma that has spread from its primary site to another anatomic site. "Relatively frequent IDH1 mutations (4.9%) were detected also in metastatic melanoma associated with NRAS mutation." (PMID 31745173, 2019).
oligoastrocytic tumor (2 papers, 2012 to 2024). Oligoastrocytomas (OA) are mixed gliomas with distinct oligodendroglial and astrocytic neoplastic components. "The incidence of IDH1/2 mutation in oligoastrocytic tumors of the frontal origin (70.0%) was significantly higher than that of non-frontal origin (45.3%) (P = 0.014)." (PMID 22427879, 2012). "The incidence of IDH1/2 mutation in oligoastrocytic tumors of the temporal origin (30.4%) was significantly lower than that of non-temporal origin (61.7%) (P = 0.008)." (PMID 22427879, 2012). "The incidence of IDH1/2 mutation in oligoastrocytic tumors of the insular origin (81.3%) was significantly higher than that of non-insular origin (50.0%) (P = 0.021)." (PMID 22427879, 2012). "For oligoastrocytic tumors, however, the incidences of IDH1/2 mutation between different sides of the brain (57.4%, 50.0% and 100.0%, respectively) were not significantly different." (PMID 22427879, 2012). "In 104 oligoastrocytic tumors (Grade II and III), the mean global incidence of IDH1/2 mutation was 54.8%." (PMID 22427879, 2012).
ovarian neoplasm (2 papers, 2022 to 2023). A benign, borderline, or malignant neoplasm involving the ovary. "They demonstrate an isocitrate dehydrogenase 1 (IDH1) mutation, which is characteristic of Ollier’s disease, within the ovarian neoplasm, suggesting a causal relationship." (PMID 37324278, 2023).
Pan (2 papers, 2020 to 2023). "Although some metabolic rate‐limiting enzymes (i.e. IDH1 and CPS1) demonstrated higher mutation rates in parts of cancer types, most metabolic rate‐limiting enzymes had lower mutation rates in Pan‐cancer human cancers." (PMID 36629054, 2023).
prostate tumors (2 papers, 2023 to 2024). "Simulated AR inhibition resulted in significant differences in the changes in AUC of nodes involved in the TGF-β, IDH1, AR, and cell cycle pathways in prostate tumors between AA and EA men." (PMID 38566104, 2024). "A significantly greater increase in AUC profiles was observed for IDH1 (34.2 vs. 9.6, P < 0.05) and SMAD (48.5 vs. 15.3, P < 0.05) after AR inhibition in prostate tumors from AA men compared to EA men." (PMID 38566104, 2024).
spindle cell hemangioma (2 papers, 2015 to 2025). Spindle cell hemangioma (SCH), also known as spindle cell hemangioendothelioma, is a rare benign vascular tumor either solitary or multiple, characterized by cavernous blood vessels separated by spindle cells reminiscent of those in KaposiBs sarcoma and located in the dermis and subcutis. "Recent molecular studies have identified IDH1 and IDH2 gene mutations in both enchondromas and spindle cell hemangiomas associated with MS." (PMID 40894918, 2025).
Stroke (2 papers, 2019 to 2024). Sudden impairment of blood flow to a part of the brain due to occlusion or rupture of an artery to the brain. "When the stroke was first turned on (IDH1 Early) there was a small but significant increase in error (NDH4 vs. IDH1 Early: P = 0.038)." (PMID 30403561, 2019). "Error quickly decreased by the end of the first stroke-dynamics/healthy target practice block (RM ANOVA for IDH trials: F = 7.7, P < 0.001; pairwise comparison for IDH1 Early vs. IDH2: P < 0.05) but did not exhibit further decreases after that." (PMID 30403561, 2019). "When the stroke dynamics were turned on, vertical undershoot decreased (NDH4 vs. IDH1 Early; P = 0.022) but did not change with further practice across IDH (RM ANOVA: F = 1.766, P = 0.147)." (PMID 30403561, 2019).
thyroid nodule (2 papers, 2019 to 2020). A small circumscribed mass in the THYROID GLAND that can be of neoplastic growth or non-neoplastic abnormality. "Some of the identified variants in the CHEK2 gene are pathogenic or likely pathogenic and the influence of found variants in the IDH1 and PPM1D gene on thyroid nodules is still uncertain and probably benign." (PMID 31085772, 2019).
thyroid tumor (2 papers, 2013 to 2022). A benign or malignant neoplasm affecting the thyroid gland. "In a series of 96 thyroid tumours whose mutational profiles of BRAF, IDH1 and NRAS mutations and RET/PTC were previously determined, we investigated MLH1 and MGMT expression and methylation status by qPCR and methylation-specific PCR after bisulphite treatment, respectively." (PMID 23414134, 2013). "Whether promoter hypermethylation of the MLH1 and MGMT genes is the underlying mechanism associated with presence of BRAF V600E, RAS, IDH1, PIK3CA mutations and/or other genetic alterations found in thyroid tumours is still unknown." (PMID 23414134, 2013).
uterine cancer (2 papers, 2023 to 2024). Primary or metastatic malignant neoplasm involving the uterine corpus and/or the cervix. "Same information for predictive models of (b) IDH1-d, (c) SMARCA4-d, (d) CDKN2A-d, (e) HERC2-d, and (f) PTEN-d in central nervous system (CNS) cancers and (g) uterine cancers." (PMID 36883553, 2023).
VEXAS syndrome (2 papers, 2024 to 2025). An adult-onset inflammatory disease that affects only males and is caused by somatic, not germline, mutations. "Whereas in VEXAS syndrome, UBA1 mutations alone are thought to drive both the inflammatory and MDS phenotypes, in UBA1‐wildtype patients with MDS/CMML, early somatic mutations in TET2/IDH1 (and/or SRSF2) are thought to contribute to the MDS/CMML and SIAD components." (PMID 39981058, 2024).
acute erythroid leukemia (1 paper, 2012). An acute myeloid leukemia characterized by a predominant immature erythroid population. "None of the cases with APL, acute monoblastic or monocytic leukemia, acute erythroid leukemia, and acute megakaryoblastic leukemia was found among IDH1-mutated group." (PMID 22397365, 2012).
adenoma (1 paper, 2020). A neoplasm arising from the epithelium. "More specifically, genes with such a therapeutic potential in non-functioning adenomas included CACNA2D4, IDH1, AURKB, GRIA2, PTGS2 and CX3CR1." (PMID 33168897, 2020).
age-related-hearing-loss (1 paper, 2022). "IDH1 is downregulated in age-related-hearing-loss and in hearing loss due to chronic lead exposure." (PMID 35573665, 2022).
ampullary cancers (1 paper, 2016). "Additionally, the role of novel approved agents and biomarkers with therapeutic intent needs to be explored in ampullary cancers (e.g. her-2 and RAS for intestinal subtype and IDH1, ARID-1, FGFR for biliary subtypes)." (PMID 27549176, 2016).
anaplastic ganglioglioma (1 paper, 2024). A WHO grade III neuroepithelial neoplasm composed of neoplastic, mature ganglion cells and anaplastic glial cells. "Although the patient’s initial pathology showed anaplastic ganglioglioma, wild-type IDH, it is classified as WHO grade 4 based on hypercellular lesions composed of glial cells with marked cytologic atypia and increased mitotic activity without IDH1 mutant." (PMID 38845691, 2024).